RN7SL578P (RNA, 7SL, cytoplasmic 578, pseudogene)
Gene: Miscellaneous RNA gene on chromosome X (3,058,220 to 3,058,502, reverse strand). Ensembl gene ENSG00000239228.
Homologues: Orthologues: chimpanzee Metazoa_SRP (97% identical), macaque Metazoa_SRP (90% identical). Paralogues in human: RN7SL702P (84% identical), RN7SL2 (80% identical), RN7SL1 (80% identical), RN7SL732P (78% identical), RN7SL125P (78% identical), RN7SL3 (78% identical), RN7SL186P (77% identical), RN7SL47P (77% identical), RN7SL126P (77% identical), RN7SL408P (77% identical), RN7SL509P (77% identical), RN7SL88P (77% identical), and 703 more.